IL1B (interleukin 1 beta)
Diseases named in the same sentence as IL1B in open-access papers (continued):
Sharing a sentence is not in itself a finding about the gene and the disease.
adenomyosis (13 papers, 2020 to 2025). The growth of endometrial tissue inside the muscular wall of the uterine corpus. "In patients with adenomyosis, the expression of several inflammatory cytokines, such as IL-1β, IL-6, IL-8, IL-10, TNF, NF-κB, MCP-1, and RANTES, is abnormal, and a variety of signaling pathways such as TLR437 and MAPK/ERK are involved." (PMID 36230643, 2022). "The systemic and local immune changes have been observed in women affected by adenomyosis, accompanied by the elevated levels of IL-6, IL-1β, IFN-α, TNF-α, and IFN-γ, and the coexistence of changes in inflammatory and anti-inflammatory signals." (PMID 34931128, 2021). "Furthermore, the numbers of natural killer cells and macrophages have been found to be elevated in the eutopic endometrium of patients with adenomyosis along with increased levels of inflammatory markers (IL-1b and IL-6)." (PMID 36744089, 2023). "IL1B, IL18 and TNF were all significantly increased in women with adenomyosis compared with controls (P = 0.002, P = 0.041 and P = 0.022, respectively)." (PMID 35773139, 2022). "Increased IL‐1β, CRH, and UCN expression in adenomyotic nodules further supports the involvement of inflammation in adenomyosis pathogenesis." (PMID 34010983, 2021). "And this activation was related to the elevated levels of IL-1β, IL-6, and TNF-α in serum and uterine tissue of adenomyosis mice." (PMID 34931128, 2021). "The Qiu treatment inhibited the expression of IL-1β, IL-6, and TNF-α in the tamoxifen-induced adenomyosis mice in a dose-dependent manner." (PMID 34931128, 2021). "The elevated levels of IL-1β, IL-6, and TNF-α in serum and uterus tissues of adenomyosis model mice were also decreased after Qiu treatment." (PMID 34931128, 2021).
anxiety disorder (13 papers, 2015 to 2025). A category of psychiatric disorders which are characterized by anxious feelings or fear often accompanied by physical symptoms associated with anxiety. "A similar report has established an increase in TNF-α and IL-1β were associated with mood and anxiety disorders." (PMID 35769902, 2022). "The gut microbiota is able to regulate systemic IL-1β concentrations, potentially modulating anxiety disorders." (PMID 32377159, 2020). "The number of studies investigating the role of IL-1β SNPs in anxiety disorders is few; hence, the present results should stimulate scientific interest on the influence of genetic asset and anxiety disorders." (PMID 32377159, 2020). "Patients with mood and anxiety disorders may have higher levels of the inflammatory cytokine, IL-1β." (PMID 32606350, 2020). "Moreover, lower IL-1β mRNA levels were also observed in obese patients with mood and/or anxiety disorders after selecting subjects with comparable BMI values (data not shown)." (PMID 30504920, 2018). "Recently, a metanalysis on 1077 anxiety disorders patients showed that, excluding patients with a chronic organic illness, moderately higher concentrations of pro-inflammatory markers (again mainly IL1-β, IL6, and TNF-alpha) were present in patients’ blood, compared to healthy controls." (PMID 34680430, 2021). "Therefore, corticosterone is utilized as a marker for assessing stress in studies of humans and animals alike; additionally, elevated levels of pro-inflammatory cytokines such as TNF-α, IL-1β, and IL-6 may serve as biological markers of anxiety disorders." (PMID 33628177, 2020). "Consistent with this analysis, we found elevated levels of IL-1β, TNF-α, IL-6, and IL-4 expression among children with TD, whereas state anxiety among those children correlated positively with IL-17 levels." (PMID 38956051, 2024). "This suggests that CORT, inflammatory factors (IL-6, IL-1β, CD86, TNF-α, TGF-β, IL-10), 5-HT, and GABA may serve as biomarkers for anxiety disorders." (PMID 40078708, 2025). "Therefore, the secondary outcome of the present study was to evaluate the potential anxiolytic effect of the novel psychobiotic formulation to treat or prevent anxiety disorders, assessed with HAM-A scale, according to the IL-1β SNP rs16944." (PMID 32377159, 2020).
brain tumor (13 papers, 2013 to 2025). "Increased serum levels of TNFα and IL-1β in patients with brain tumors have been associated with adverse prognosis." (PMID 37542119, 2023). "In the context of brain tumors, although resident antigen-presenting microglia express TLRs, they are unable to secrete interleukin (IL)-1B, IL-6, or tumor necrosis factor-alpha (TNF-α) to mount an effective innate immune response." (PMID 38256021, 2024). "Data also suggested that the neural stem cell–like GBM stem cell (GSC), also known as brain tumor-initiating cell (BTIC), fraction that is associated with therapeutic resistance may be enriched with knockout of Il1a and Il1b compared with loss of Il1b alone." (PMID 37966120, 2023). "IL-1β is critical for immune cell infiltration into brain tumors." (PMID 37450588, 2023). "Variants of NPAS3, a neuronal transcription factor thought to be involved in brain tumor suppression, were found to be associated with 11 of the MetS phenotypes (Fatkg, Leankg, SubQF, TAF, REE, TG, TC, LDL-c, pulse, IL1b and IL-6), suggesting a pleitropic effect." (PMID 23628382, 2013). "However, the controversial result shows that the increase of IL-1β enhances cisplatin-induced cell death in brain tumor T98G-resistance cells." (PMID 23383347, 2013). "In humans, the proinflammatory cytokines IL-1β, IL-6, IL-8, IL-12, GM-CSF and TNF-α have been involved in brain tumor initiation and progression." (PMID 36232813, 2022). "we have reported five co-regulated clusters via seven important co-expression genes (COL1A2, LUM, SPARC, THBS2, IL1B, CXCL8, THY1) interacting between five clusters of the brain tumours." (PMID 35045088, 2022). "Like IL-1B also the enhanced expression of TNF might induce IL-6 and subsequently reduce brain tumor growth by enhancing macrophage recruitment." (PMID 30224928, 2018).
brucellosis (13 papers, 2013 to 2025). Brucellosis is a bacterial infection that spreads from animals to people via unpasteurized dairy products or by exposure to contaminated animal products or infected animals. "While the C-terminal region of mouse pyrin is uncharacterized, the human counterpart contains a SPRY domain that mediates interactions with Casp1 and pro-IL-1β and that is the site of mutations associated with Mediterranean fever." (PMID 24875775, 2014). "Comparable findings have been reported in human patients with brucellosis, where monocytes exhibited diminished IL-1β, IL-6, and IL-10 secretion in response to LPS stimulation." (PMID 40406273, 2025). "The concentration of several inflammatory mediators was measured in the serum of these patients, and levels of IFN-γ, IL-1β and IL-6 were found significantly increased before the treatment of acute brucellosis." (PMID 35979363, 2022). "Mediterranean fever (MEFV) gene mutation encoding pyrin are found in almost all patients with FMF, leading to excess inflammation through increased IL-1β production." (PMID 32737687, 2020). "Increased levels of production of IL-1β were detected in the sera of untreated brucellosis patients and in the supernatants of Brucella suis-infected macrophage cell cultures, suggesting an important role of IL-1β in the pathogenesis of brucellosis." (PMID 29343543, 2018). "After treatment, the level of IL-1β in the serum of brucellosis patients was significantly decreased and normalized." (PMID 29343543, 2018). "Conversely, 3-MA treatment that inhibited autophagy led to elevated expression of TNF-α, IL-6, IL-1β, and IL-10 than those from untreated monocytes from brucellosis patients." (PMID 28659924, 2017). "Similarly, we observed that Mediterranean Buffaloes with brucellosis release lower levels of three pro-inflammatory cytokines than healthy controls: IL-1α, IL-1β, IL-6." (PMID 40406273, 2025). "Notably, the chronic form of bovine brucellosis was associated with increased expression of IFN-γ, IL-1β, IL-6 and iNOS genes, along with reduced expression of TNF-α, IL-4 and IL-12p40 genes." (PMID 39825331, 2025). "Additionally, IL-1β has been identified on NETs of Familial Mediterranean Fever patients during their attack episodes." (PMID 40547021, 2025). "Microarray analysis of lung tissue homogenates and BALF cells revealed that RTD-1 significantly reduced proinflammatory gene expression, particularly inflammasome-related genes (nod-like receptor protein 3, Mediterranean fever gene, interleukin (IL)-1α, and IL-1β) relative to the control." (PMID 34572625, 2021). "However, more studies are required to further understand the mechanism by which IL-1β influences brucellosis." (PMID 29343543, 2018). "From the initial 15, we narrowed it down to five: our analysis showed that the quantitative determination of IFN-γ, in parallel with the chemokine IP-10 and three pro-inflammatory cytokines (IL-6, IL-1α and IL-1β) could be useful in the diagnosis of brucellosis in Mediterranean Buffaloes." (PMID 40406273, 2025). "Additionally, we also detected high expression of typical inflammatory cytokines (e.g., S100A8/9/12, IL1B, IL6, CXCL8, CCL2, CXCL10) in brucellosis patients during the acute phase." (PMID 39135683, 2024). "As the major contributor of potential inflammatory storm, many inflammatory response genes (e.g., ITGB2, OSM, FPR1, CEBPB, NINJ1) and canonical pro‐inflammatory cytokines (e.g., CXCL8, CCL3, CCL4, TNF, IL1B, S100A12) were expressed at higher levels in brucellosis patients than in healthy donors." (PMID 39135683, 2024). "Additionally, the production of IL-1β, IL-6, IL-10, and TNF-α from monocytes in patients with brucellosis was suppressed through the LC3-dependent autophagy pathway during Brucella infection." (PMID 28659924, 2017).
brucellosis (continued). "Procarta cytokine analysis from the plasma of these individuals, supported the finding that brucellosis patients, especially for acute patients, had a higher level of multiple pro‐inflammatory cytokines, such as CXCL8/IL8, CCL3/MIP‐α, CCL4/MIP‐β, TNF/TNF‐α, IL1B/IL1‐β." (PMID 39135683, 2024). "Moreover, its expression may reduce IL-1β expression in patients with acute brucellosis, which may be a strategy for Brucella not to lose its niche." (PMID 36068262, 2022).
carotid atherosclerosis (13 papers, 2017 to 2024). A thickening and loss of elasticity of the walls of carotid arteries that occur with formation of atherosclerotic plaques. "Accordingly, we have recently reported that HCWs with a “dysfunctional circadian clock” and with increased levels of IL1b carry a higher risk of developing carotid atherosclerosis through an overload of IL6 being released." (PMID 35886686, 2022). "In addition, NLRP3 inflammasomes are closely associated with colchicine, IL-1β, and IL-6 and are thought to be potentially important targets for anti-inflammatory treatment of atherosclerotic heart disease." (PMID 33598482, 2020). "Consistent with previous works, our result showed that high expressions of NLRP3 inflammasome components such as c-caspase-1 and c-IL-1β were observed in carotid atherosclerosis." (PMID 35464766, 2022). "Surprisingly, the carotid artery specimen revealed a decreased expression of HMGB1 and S100B with a concomitant increase in the pro-inflammatory cytokines IL-17, IL-18 and IL-1β suggesting the priming role of DAMPs in initiating carotid atherosclerosis." (PMID 35531433, 2022). "Therapeutic monoclonal antibody targeting IL-1β confirms the inflammatory theory of atherosclerotic heart disease but is still far from clinical treatment." (PMID 33598482, 2020). "Thus, despite some unsolved mysteries, the results of the clinical research on colchicine, IL-1β antibodies, and IL-6Ra have undoubtedly led to a victory in the anti-inflammatory treatment of atherosclerotic heart disease." (PMID 33598482, 2020). "Herein we extend these reports by demonstrating increased plasma levels of IL-27 in 140 patients with carotid atherosclerosis, and increased mRNA levels of IL-27 subunits and IL-27RA, as well as increased expression of IL-1β and NLRP3 within the carotid lesion from 159 patients." (PMID 29176764, 2017). "Patients with carotid atherosclerosis showed increased plasma levels of CXCL13, where CXCL13 exerted anti-apoptotic effects and counteracted the suppressive effects of IL-1b on collagen synthesis in smooth muscle cells (SMCs)." (PMID 38880863, 2024). "In a recent smaller study, IL-1β and IL-6 were found higher expressed in pericoronary artery adipose tissue, probably comparable with the EAT in our study, in patients with atherosclerotic heart disease compared to controls with mitral valve surgery." (PMID 36644557, 2022). "We suggest that ferroptosis of cells increases the expression of the IL-1B gene by inhibiting GPX4 and SIRT1, which activates the inflammatory response, produces a large amount of ROS, and finally leads to the occurrence of carotid atherosclerosis." (PMID 36393970, 2022). "Among them, IL1B and HMOX1 are possible biomarkers or targets of ferroptosis and carotid atherosclerosis." (PMID 36393970, 2022). "Based on the results of bioinformatics analysis, we further identified 10 most critical ferroptosis-related genes in carotid atherosclerosis by PPI analysis including HMOX1, IL1B, and NOX4." (PMID 36393970, 2022). "Because little is known about the NLRP3 inflammasome, IL-1β and IL-18 in patients with T2DM and AS, here we performed a cross-sectional study investigating these inflammatory components in patients with T2DM complicated with carotid atherosclerosis (CAS)." (PMID 29151018, 2017).
chlamydial infection (13 papers, 2006 to 2025). "There is evidence to suggest that the elevated local levels of TNF and IL-1β associated with chlamydial infection and inflammation act as an important trigger of matrix degradation by inducing MMP-9 activity in inflamed tissue." (PMID 16643654, 2006). "Stimulation of the secretion of proinflammatory cytokines and chemokines such as IL-1β supports the host’s defense against chlamydial infection and participates in the immune response in both acute and chronic infection." (PMID 40647668, 2025). "It is important to define the role of IL-1β in this context: while this IL protects the host in the defense against chlamydial infection, we still believe that it is a promoting disease-related factor in Chlamydia infection." (PMID 34093528, 2021). "Once activated, the NLRP3/ASC inflammasome mediates caspase-1-dependent IL-1β signaling activation that regulates the maturation of IL-1β and IL-18, and interferes with chlamydial infectivity, thus defending the host against chlamydial infection." (PMID 31333596, 2019). "However, unlike LPS/ATP, the inflammatory molecular switch RIP3 was not involved in the activation of NLRP3 inflammatory vesicles in murine Chlamydia-stimulated BMDM, suggesting that chlamydial infection leads to caspase-1 cleavage and IL-1β release by a different mechanism than LPS/ATP." (PMID 38333214, 2024). "We also detected an increase of MIF/GIF after chlamydial infection, a pro-inflammatory cytokine promoting the production of tumor necrosis factor (TNF), IFN-γ, IL-1β, IL-2, IL-6 and IL-8." (PMID 25019934, 2014). "We found that chlamydial infection alters the morphology of monocytes and trigger the release of pro-inflammatory cytokines TNF-α, IL-8, IL-1β and IL-6." (PMID 21249123, 2011). "in 2017 showed that both LPS/ATP and murine chlamydial infection of mouse bone marrow-derived macrophages (BMDM) could lead to caspase-1 cleavage and IL-1β released." (PMID 38333214, 2024). "CtD infected NLRP3−/−, Casp1/11−/−, IL-1β−/−IL-18−/−, and IL-1R−/− mice all exhibited significantly greater infectious loads at day 3 and 7 pi showing NLRP3/Caspase1 inflammasome signaling pathway is critical for controlling early chlamydial infection." (PMID 34526512, 2021). "In summary, our data show that AHCC feeding to stressed mice results in (i) restoration of the functions of immune cells; (ii) reduced genital tract chlamydia shedding in AHCC-fed mice; and (iii) enhanced production of IFN-γ or TNF-α by T cell co-cultured with IL-1β producing monocytes." (PMID 27790645, 2015).
chronic granulomatous disease (13 papers, 2012 to 2025). Chronic granulomatous disease (CGD) is a rare primary immunodeficiency, mainly affecting phagocytes, which is characterized by an increased susceptibility to severe and recurrent bacterial and fungal infections, along with the development of granulomas. "Initially, NADPH-oxidase-derived ROS production was also implicated in IL-1β release in the periodic fever cryopyrin-associated periodic syndrome, but analyses of chronic granulomatous disease patients discounted a role for NADPH-oxidases in these disorders." (PMID 24356959, 2014). "Along this line, the increased IL-1β release intrinsically associated to chronic granulomatous disease (CGD) was found to be reverted by the use of IL-1 receptor antagonist (IL-1Ra), leading to restrained neutrophil recruitment and T helper 17 responses, thereby protecting from IA." (PMID 25999936, 2015). "Further, it is interesting to note that while ROS is crucial for secretion of IL-1β via inflammasome activation, mice defective in ROS generation and patients with chronic granulomatous diseases (CGD) have a pro-inflammatory phenotype." (PMID 25324778, 2014). "For example, anakinra has been used to reduce IL-1β levels in a mouse model of chronic granulomatous disease (CGD), an immunodeficiency characterized by defective production of ROS." (PMID 28650995, 2017). "It has reported that cells from patients with chronic granulomatous disease (CGD), characterized by an incapacity of phagocytosis to produce ROS due to a deficiency in the NADPH oxidase system produce more inflammatory cytokines including IL-1β." (PMID 24409188, 2014). "In fact, this is also similar to the condition of chronic Granulomatous Disease where impaired ROS production due to a genetic defect does not affect IL-1β secretion." (PMID 22474421, 2012). "In human peripheral blood mononuclear cells (PBMCs) from chronic granulomatous disease (CGD) patients, Aspergillus nidulans strains unable to produce GAG were more virulent and induced higher levels of IL-1β secretion than A. fumigatus." (PMID 41249509, 2025).